MDM2 (MDM2 proto-oncogene)
Diseases named in the same sentence as MDM2 in open-access papers (continued):
Sharing a sentence is not in itself a finding about the gene and the disease.
infarction (2 papers, 2013 to 2019). A localised pathological necrosis of tissue resulting from obstruction of the blood supply usually by a thrombus, an embolus, or vascular torsion. "Further investigations are thus warranted to better understand how the interplay between MDM2 and E2F1 impacts myocardial physiology and recovery post-infarction." (PMID 31921839, 2019).
invasive carcinoma (2 papers, 2004 to 2010). A carcinoma that is not confined to the epithelium, and has spread to the surrounding stroma. "However, Mdm2 expression in regenerative mucosa was significantly higher than in normal, LGD, HGD crypts and in UC-associated and non-UC-associated invasive carcinoma lesions." (PMID 15292938, 2004).
ischemic cardiomyopathy (2 papers, 2017 to 2026). Ischemic cardiomyopathy is a cardiomyopathy in which a weakness in the muscle of the heart due to inadequate oxygen delivery to the myocardium with coronary artery disease being the most common cause. "The hub genes, including STAT3, MDM2, LRP1, IRS2, PRKCD, CCND2, and CISH, were validated to be highly expressed in adipocytes in ischemic cardiomyopathy patients with end-stage heart failure." (PMID 41869532, 2026).
kidney failure (2 papers, 2016 to 2025). An acute or chronic condition that is characterized by the inability of the kidneys to adequately filter the blood. "MALDI-MSI analysis was performed on sagittal freshly frozen brain sections in control and Mdm2-cKO mice with kidney failure." (PMID 39946208, 2025). "We employed spatial and bulk metabolomics to investigate a mouse model of rapid kidney failure induced by mouse double minute 2 (Mdm2) conditional deletion in the kidney tubules to interrogate kidney and brain metabolism." (PMID 39946208, 2025). "Based on previous studies highlighting the role of mouse double minute 2 (Mdm2) in human and experimental kidney disease, we studied rapid kidney failure in the doxycycline-induced conditional knockout of Mdm2 targeting renal tubular epithelial cells (Mdm2-cKO)." (PMID 39946208, 2025). "First, our findings indicate that in the Mdm2-cKO model of kidney failure, there are no observed effects consistent with diffuse multiorgan failure, thus supporting our hypothesis of a kidney/brain axis." (PMID 39946208, 2025).
liver diseases (2 papers, 2022 to 2025).
lymphoid neoplasm (2 papers, 2021 to 2024). A neoplasm composed of a lymphocytic cell population which is usually malignant (clonal) by molecular genetic and/or immunophenotypic analysis.
malignant phyllodes tumor (2 papers, 2018 to 2023). A phyllodes tumor with sarcomatous stroma. "MDM2 and/or CDK4 protein overexpression and gene amplification are beneficial ancillary studies that can help establish the diagnosis of primary breast ALT/WDLPS and DDLPS, and effectively rule out the diagnoses of malignant phyllodes tumor and metaplastic breast carcinoma." (PMID 37888062, 2023).
malignant rhabdoid tumors (2 papers, 2015 to 2019).
mental disorder (2 papers, 2015 to 2024). A disease that has its basis in the disruption of mental process. "While MDM2 is primarily recognized for its role in cancer biology, emerging evidence suggests it may also play a significant role in mental disorders, especially through its regulation of stress response, ubiquitination activity, and cell survival in the brain." (PMID 39684694, 2024).
Merkel cell carcinoma (2 papers, 2020 to 2022). "The inhibition of MDM2 could be also effective in a neuroendocrine carcinoma of the skin called Merkel cell carcinomas, which is caused by Merkel cell polyomavirus." (PMID 32268515, 2020).
metastasis (2 papers, 2015 to 2018). The spread or migration of cancer cells from one part of the body (where they first appeared) to another. "Association of the expression of MDM2, IGF1, STAT1, and RAC1 and clinical characteristics such as age, gender, Campanicci grade, pathological fracture, and lung metastasis was also analyzed using the Kendall's tau-b test." (PMID 29651441, 2018).
mucoepidermoid carcinoma (2 papers, 2010 to 2022). A carcinoma morphologically characterized the presence of cuboidal mucous cells, goblet-like mucous cells, squamoid cells, cystic changes, and a fibrotic stromal formation.
myeloid leukemia (2 papers, 2015 to 2019). A clonal proliferation of myeloid cells and their precursors in the bone marrow, peripheral blood, and spleen.
neuroendocrine carcinoma (2 papers, 2020 to 2022). A malignant neuroendocrine neoplasm composed of cells containing secretory granules that stain positive for NSE and chromogranin. "Here, we investigated whether MDM2 upregulates MYC as well as MYCN in selected neural and neuroendocrine cancers." (PMID 33425720, 2020). "To assess whether MDM2 has a general role in regulation of MYC family proteins, we queried the effects of MDM2 knockdown in a series of neuroendocrine cancer cell lines." (PMID 33425720, 2020).
oral cancer (2 papers, 2017 to 2025). "Of the MDM2 promoter polymorphisms identified, 2 single nucleotide polymorphisms (SNPs) of MDM2, MDM2rs2279744 and MDM2rs937283, have been reported in the risk of SCCHN or HPV-associated oral cancer." (PMID 28045062, 2017).
oropharyngeal carcinoma (2 papers, 2012 to 2019). Carcinoma, predominantly squamous cell, arising from the epithelial cells of the oropharynx. "In other types of cancer such as oropharyngeal carcinoma, MDM2 SNP309 TT genotype has higher association with tumor recurrence when compared to TG and GG genotypes." (PMID 31350972, 2019).
Osteopenia (2 papers, 2023). Osteopenia is a term to define bone density that is not normal but also not as low as osteoporosis. "First, by using traceable conditional animal models, we demonstrated that heterozygous deletion of Mdm2 resulted in osteopenia." (PMID 36909480, 2023). "Thus, genetic depletion of Mdm2 in MSCs was associated with increased MSCS apoptosis levels and osteopenia in adult mice." (PMID 36909480, 2023).
osteosclerosis (2 papers, 2023). Abnormally high bone density.
ovarian serous borderline tumors (2 papers, 2021 to 2025). "Previous studies have shown that up to 80% of ovarian serous borderline tumors exhibit MDM2 overexpression, while the expression of MDM2 is notably low in benign ovarian tumors or normal ovaries." (PMID 34445495, 2021).
phyllodes tumor (2 papers, 2023 to 2025). A benign, borderline, or malignant fibroepithelial neoplasm arising from the breast and rarely the prostate gland.
pituitary adenoma (2 papers, 2017 to 2025). "HMGA, MDM2, and RB regulate different points of the cell cycle and therefore play critical roles in pituitary cell proliferation and pituitary adenoma development." (PMID 28255749, 2017).
preeclampsia (2 papers, 2019 to 2024). Preeclampsia is a hypertensive disorder of pregnancy that is characterized by new-onset hypertension with proteinuria presenting after 20 weeks of gestation, and depending on mild or severe forms may initially present with severe headache, visual disturbances, and hyperreflexia. "On the other side, MDM2, a gene associated with preeclampsia susceptibility, was significantly down-regulated by coculturing." (PMID 31596842, 2019).
primary effusion lymphoma (2 papers, 2014 to 2016). A large B-cell lymphoma located in the body cavities, characterized by pleural, peritoneal, and pericardial fluid lymphomatous effusions and that is always associated with human herpes virus-8 (HHV-8). "To further validate the results of the screen in cells that are naturally infected by KSHV, we silenced MDM2 expression in BC-3 cells, a patient-derived primary effusion lymphoma (PEL) cell line." (PMID 26891221, 2016).
progerias (2 papers, 2014 to 2018).
prostate (2 papers, 2011 to 2021).
schizophrenia (2 papers, 2013 to 2023). A major psychotic disorder characterized by abnormalities in the perception or expression of reality. "In this study, we first performed family-based association analysis of genetic variants in the PSD genes; DLG4, DLG1, PICK1 and MDM2 using Japanese schizophrenia pedigrees." (PMID 23936182, 2013). "By performing a three staged genetic analysis in independent cohorts of Japanese and Chinese schizophrenia patients, our study aimed to investigate the role of genomic variants in DLG4, DLG1, PICK1 and MDM2 in determining the predisposition to schizophrenia." (PMID 23936182, 2013). "Finally, MDM2 had been found to be underexpressed in the dorsolateral prefrontal cortex of schizophrenia patients." (PMID 36768211, 2023).
Sepsis (2 papers, 2016 to 2019). Sepsis is defined as life-threatening organ dysfunction caused by a dysregulated host response to infection. "We have further demonstrated that TSLP levels decrease in LPS-stimulated macrophages and mice with sepsis by nutlin-3a, indicating that MDM2 is important in regulating TSLP." (PMID 31480519, 2019). "Furthermore, we have now identified that mRNA and protein expressions of MDM2 increase in LPS-stimulated peritoneal macrophages and organs of mice with sepsis." (PMID 31480519, 2019). "Altogether, the present results show that TSLP exacerbates septic inflammation via the MDM2 signaling pathway, suggesting that TSLP may be a potential target for the treatment of sepsis." (PMID 31480519, 2019).
serous adenocarcinoma (2 papers, 2016 to 2025). An adenocarcinoma that is characterized by the presence of papillary patterns and cellular budding. "An exclusive MDM2 amplification was identified within the serous adenocarcinoma fraction, while an ARID2 loss and an AKT2 amplification were uniquely present in the SC-NEC compartment." (PMID 40833530, 2025).
Sjögren's syndrome (2 papers, 2015 to 2017). "Titer of anit-MDM2 was negatively associated with hemoglobin level, platelet count, complement 3 level and complement 4 level, positively associated with European Sjogrens syndrome disease activity index (ESSDAI) and level of IgG." (PMID 28147328, 2017). "Titer of anti-MDM2 was negatively associated with hemoglobin level, platelet count, complement 3 (C3) level and complement 4 (C4) level, positively associated with European Sjogren's syndrome disease activity index (ESSDAI) and level of IgG." (PMID 28147328, 2017). "We further analyzed the correlation of titer of anti-MDM2 and European Sjogren's syndrome disease activity index (ESSDAI), complement 3 (C3), complement 4 (C4), immunoglobulin and other laboratory findings including level of platelet (PLT), hemoglobin (HB) and white blood cell count (WBC)." (PMID 28147328, 2017).
steatosis (2 papers, 2022 to 2025). Increased lipid within the cytoplasm of cells. "We believe that the improvement in steatosis is mainly caused by the direct effect of MDM2 inactivation on ApoB expression and TG‐VLDL secretion, whereas the alleviation of inflammation and fibrosis may be secondary to the relief from lipotoxicity in hepatocytes." (PMID 35524581, 2022). "Analysis of E‐MEXP‐3291 dataset showed that mRNA expression of hepatic MDM2 was increased in humans with steatosis and NASH compared with that in normal individuals." (PMID 35524581, 2022). "As previously discussed, TM6SF2 gene knockout, inhibition of MDM2–ApoB interaction, HNF4α, GLS1 inhibition, and mTORC1 activation on VLDL lipidization have shown great potential for reducing steatosis by regulating VLDL to affect MASLD." (PMID 40723862, 2025). "In summary, we demonstrate that MDM2 inactivation by genetic and pharmacological approaches result in protective effects in two independent mouse models of MAFLD with steatosis, inflammation, and/or fibrosis." (PMID 35524581, 2022).
ulcerative colitis (2 papers, 2020 to 2025). An inflammatory bowel disease involving the mucosal surface of the large intestine and rectum. "It was found that a single-nucleotide polymorphism at rs309 in the MDM2 gene was associated with ulcerative colitis." (PMID 32224842, 2020). "Since the distribution of the MDM2 polymorphism in individuals with ulcerative colitis was approximately the same as, it can be concluded that ulcerative colitis is a precedes for the development of ulcers into malignancies." (PMID 32224842, 2020). "The overall aim of this study was to investigate the rs309 polymorphism of MDM2 and its association with ulcerative colitis, and a secondary aim was to explore the association between this polymorphism and the risk of cancer." (PMID 32224842, 2020). "In this study, it was found that the T>G polymorphism at the rs309 locus of the MDM2 gene was associated with ulcerative colitis through a statistical analysis." (PMID 32224842, 2020). "People with the GG phenotype of the MDM2 gene were more prone to ulcerative colitis (odds ratio, 7.142; 95% confidence interval, 2.400 to 9.542) than those with the TT genotype." (PMID 32224842, 2020). "The distribution of the MDM2 genotype in the ulcerative colitis patients was as follows: TT, 37.93%; TG, 27.59%; and GG, 34.48%." (PMID 32224842, 2020). "The distribution of the MDM2 genotype in ulcerative colitis patients was as follows: TT, 37.93%; TG, 27.59%; and GG, 34.48%." (PMID 32224842, 2020).
uterine sarcoma (2 papers, 2020 to 2021). "In conclusion, our data suggest that detection of MDM2 amplicons could be a useful tool in uterine sarcoma pathology and implicate MDM2 as a potential therapeutic target in HGESS‐BCOR." (PMID 32352245, 2020).
ZIKV infection (2 papers, 2017 to 2021).
Acidosis (1 paper, 2019). Abnormal acid accumulation or depletion of base.
acne (1 paper, 2023). An inflammatory process of the sebaceous glands which is characterized by comedones, nodules, papules and/or pustules on the skin.
actinic keratosis (1 paper, 2022). A precancerous lesion of the skin composed of atypical keratinocytes.
adenoid cystic carcinoma (1 paper, 2025). A malignant tumor arising from the epithelial cells.
age-related macular degeneration (1 paper, 2025). Age-related loss of vision in the central portion of the retina (macula), secondary to retinal degeneration.
aneuploidy (1 paper, 2023). Chromosomal disorder consisting of the presence a chromosomal abnormality in which there is an addition or loss of chromosomes within a set. "To date, seldom study has analyzed the MDM2 rs2279744 T > G polymorphism and fetal aneuploidy." (PMID 37648962, 2023).